GUCY2C (guanylate cyclase 2C)
Description:
Guanylyl cyclase that catalyzes synthesis of cyclic GMP (cGMP) from GTP. Receptor for the E.coli heat-stable enterotoxin; E.coli enterotoxin markedly stimulates the accumulation of cGMP in mammalian cells expressing GUCY2C. Also activated by the endogenous peptides guanylin and uroguanylin.
Synonyms: GC-C; GUC2C; STAR; HSER; GCC; DIAR6; MECIL; MUCIL
Tractability: Small molecule: a structure with a bound ligand is known; it belongs to a druggable protein family. Antibody: UniProt places it where antibodies can reach, with high confidence; its Gene Ontology location is reachable by antibodies, with high confidence; UniProt predicts a signal peptide or a membrane-spanning region. PROTAC: ubiquitination databases record sites on it. Other modalities: an approved drug acts on it.
Target class: Lyase; Enzyme; Guanylate cyclase; Receptor guanylate cyclase
Gene: Protein-coding gene on chromosome 12 (14,612,632 to 14,696,599, reverse strand). Ensembl gene ENSG00000070019.
Subcellular location: Cell membrane; Endoplasmic reticulum membrane
Subcellular location (Human Protein Atlas): Vesicles
Pathways (Reactome):
Digestion and absorption: Digestion
Disease: Intestinal infectious diseases
Gene Ontology:
Molecular function: guanylate cyclase activity; protein binding; peptide receptor activity; ATP binding; phosphorus-oxygen lyase activity; protein kinase activity; toxic substance binding
Biological process: cGMP biosynthetic process; receptor guanylyl cyclase signaling pathway; cyclic nucleotide biosynthetic process; intracellular signal transduction
Cellular component: endoplasmic reticulum membrane; plasma membrane
Genetic constraint (gnomAD): Loss-of-function variants: 28 observed, 34.35 expected, observed/expected ratio (o/e) 0.82, 90% interval 0.6 to 1.12. The upper end of that interval is the gene's LOEUF score, 1.12, which puts it in group 4 of 6, group 1 being the genes least tolerant of losing a copy. Missense variants: 417 observed, 516.73 expected, observed/expected ratio (o/e) 0.81, 90% interval 0.74 to 0.88. Synonymous variants: 172 observed, 182.94 expected, observed/expected ratio (o/e) 0.94, 90% interval 0.83 to 1.07.
Homologues: Orthologues: chimpanzee GUCY2C (99% identical), macaque GUCY2C (98% identical), dog GUCY2C (88% identical), pig GUCY2C (87% identical), rabbit GUCY2C (84% identical), guinea pig GUCY2C (83% identical), rat Gucy2c (83% identical), mouse Gucy2c (82% identical), tropical clawed frog gucy2c (62% identical), zebrafish gucy2cb (54% identical), zebrafish gucy2ca (51% identical). Paralogues in human: NPR2 (29% identical), GUCY2D (29% identical), GUCY2F (29% identical), NPR1 (29% identical), GUCY1A2 (15% identical), ADCY3 (14% identical), ADCY1 (14% identical), ADCY7 (14% identical), GUCY1A1 (14% identical), ADCY8 (14% identical), ADCY6 (13% identical), ADCY4 (13% identical), and 5 more.
Diseases named in the same sentence as GUCY2C in open-access papers:
GUCY2C is named in the same sentence as 62 diseases in open-access papers, as found by Europe PMC text mining. Sharing a sentence is not in itself a finding about the gene and the disease. The quoted sentences say what the papers report.
colorectal cancer (48 papers, 1999 to 2026). A primary or metastatic malignant neoplasm that affects the colon or rectum. "• Describing TCRs that identify both the intestinal epithelial cell receptor and the GUCY2C antigen associated with colorectal cancer.• Developing a framework for investigating mechanisms of self-antigen-specific tolerance." (PMID 37927469, 2023). "The intestinal epithelial receptor Guanylyl Cyclase C (GUCY2C) is a tumor-associated cell surface antigen expressed across gastrointestinal malignancies that can serve as an efficacious target for colorectal cancer immunotherapy." (PMID 37591971, 2023). "Because of these wide-ranging roles, dysregulation of the GUCY2C-cGMP signaling axis has been implicated in the pathogenesis of bowel transit disorders, inflammatory bowel disease, and colorectal cancer." (PMID 30131940, 2018). "An emerging paradigm suggests that guanylin loss disrupting the GUCY2C paracrine signaling axis, and epithelial cell homeostasis, is a required step in colorectal cancer initiation." (PMID 29035170, 2017). "The GUCY2C signaling axis is universally silenced in colorectal cancer reflecting loss of expression of guanylin in transforming crypts." (PMID 29262534, 2017). "In striking contrast to the prevailing paradigm, these analyses revealed that the majority of the GUCY2C associated with intestinal epithelial and colorectal cancer cells resided in the intracellular compartment, primarily in lysosomes." (PMID 25294806, 2014). "Collectively, these findings underlie the paracrine hormone hypothesis of colorectal cancer, which suggests that guanylin insufficiency silences the tumor suppressive properties of the GUCY2C-cGMP axis, producing a microenvironment conducive to transformation." (PMID 30131940, 2018). "Thus, the geographic imbalance in colorectal cancer, in part, may reflect chronic exposure to ST-producing organisms that restore GUCY2C signaling silenced by hormone loss during transformation." (PMID 28895923, 2017). "For example, cadherin 17 (CDH17) and guanylate cyclase 2C (GUCY2C) are highly expressed in colorectal cancer but have very low expression in normal tissues." (PMID 40057807, 2025). "Here, we found that CDH17 and GUCY2C are co-overexpressed in colorectal cancer cells and developed a bispecific antibody-drug conjugate (BsADC) targeting CDH17 and GUCY2C, conjugated with the ferroptosis inducer RSL3 (a GPX4 inhibitor)." (PMID 40721409, 2025). "We also found that CDH17 and GUCY2C were co-high expressed in most colorectal cancer patients and rectum adenocarcinoma patients." (PMID 40721409, 2025). "Guanylyl cyclase C (GUCY2C), “an intestinal tumor suppressor”, has been described as a key factor of carcinogenesis in colorectal carcinoma." (PMID 39335194, 2024). "Here, we examined the immunogenicity of an Lm-based vaccine expressing the colorectal cancer antigen guanylyl cyclase C (Lm-GUCY2C)." (PMID 35355987, 2022). "PF-07062119 is a T cell engaging BsAb targeting guanylyl cyclase C (GUCY2C), a protein that is over-expressed in colorectal cancers (CRC) and other gastrointestinal malignancies." (PMID 34143379, 2021). "Together, intestinal compartmentalization and near-universal expression by primary and recurrent colorectal cancer, establish GUCY2C as an attractive target for immunotherapeutic prevention of colorectal cancer recurrence." (PMID 31010434, 2019). "C-src, a tyrosine kinase overexpressed in colorectal cancer, phosphorylates tyrosine 820 on the catalytic domain of GUCY2C, inhibiting receptor activation." (PMID 30131940, 2018). "The intestinally restricted receptor guanylyl cyclase C (GUCY2C) is a target that has been investigated for the treatment of colorectal cancer and numerous animal, and clinical studies have demonstrated both efficacy and safety." (PMID 28914772, 2017).
colorectal cancer (continued). "Here, we reveal that over-nutrition and consumption of excess calories suppresses guanylin and uroguanylin expression, simultaneously disrupting GUCY2C paracrine and endocrine signaling axes at the nexus of obesity and colorectal cancer." (PMID 29035170, 2017). "Current evidence supports GUCY2C as a safe and effective target for colorectal cancer immunotherapy." (PMID 28914772, 2017). "JE Lin, F Colon-Gonzalez, E Blomain, GW Kim, A Aing, B Stoecker, J Rock, AE Snook, T Zhan, T Hyslop, M Tomczak, RS Blumberg, SA Waldman: Calories suppress guanylin silencing the GUCY2C tumor suppressor in colorectal cancer in obesity.Can." (PMID 29035170, 2017). "CT26 mouse colorectal cancer cells, which are devoid of endogenous GUCY2C expression, were engineered to express mouse GUCY2C (CT26.GUCY2C)." (PMID 25294806, 2014). "Gucy2c and Srp9 have been shown to be overexpressed in colorectal cancer cells and were recently shown to function as a candidate biomarker for colon cancer." (PMID 23555558, 2013). "Both CDH17 and GUCY2C are highly expressed in colorectal cancer." (PMID 40721409, 2025). "Hence, the GUCY2C signaling axis represents a novel therapeutic target for preventing colorectal cancer." (PMID 30131940, 2018). "Taken together, these findings suggest an intriguing hypothesis that colorectal cancer arises in a microenvironment of functional GUCY2C inactivation, which can be repaired by oral ligand replacement." (PMID 30131940, 2018). "Therefore, we speculated that GUCA2A affects the development of colorectal cancer by regulating GUCY2C." (PMID 32462020, 2020). "The main targets for CAR T cell therapy in colorectal cancer include CEA, MSLN, Guanylyl Cyclase C (GUCY2C), EpCAM, HER2, and Doublecortin-like kinase 1(DCLK1)." (PMID 38622705, 2024). "Overall, in colorectal cancer, NKG2D, CD133, GUCY2C (Guanylate Cyclase 2C), and TAG-72 are the most prominent target antigen to reaching the promising therapeutic goal." (PMID 33494834, 2021). "GUCY2C modulates homeostatic processes by opposing AKT1 phosphorylation and downstream signaling in intestine and colorectal cancer." (PMID 22384056, 2012). "Guanylyl cyclase C (GUCY2C), a membrane-spanning receptor synthesizing the second messenger cyclic GMP (cGMP), is selectively expressed by intestinal epithelial cells and a subset of neurons and near-universally overexpressed in colorectal cancer." (PMID 31010434, 2019). "To confirm these findings in a more physiologic setting, we used retroviral transduction to over-express either EGFP, CDX2, or CDX2/AS in HT29 and SW480 colorectal cancer cells that express endogenous CDX2 and CDX2/AS and compared expression of endogenous GUCY2C transcripts." (PMID 25101906, 2014). "In that context, GUCY2C has emerged as a novel vaccine target to treat and prevent colorectal cancer metastases without normal tissue damage." (PMID 25294806, 2014).
Obesity (15 papers, 2013 to 2026). Accumulation of substantial excess body fat. "Expression of these macrophages expressing Gucy2c and guanylin was shown to be mechanistically linked to resistance to diet-induced obesity." (PMID 26237477, 2014). "Therefore, we first explored the impact of weight gain induced by diet-induced obesity and weight loss achieved by bariatric surgery in pancreas expression of guanylin peptides and their receptor GUCY2C in rats." (PMID 37274331, 2023). "We herein show, for the first time, that obesity reduces GUCA2A mRNA and protein expression in the pancreas, and weight loss achieved by sleeve gastrectomy upregulated both GUCA2A and GUCY2C expression." (PMID 37274331, 2023). "Intestinal and circulating GUCA2B are decreased in experimental and human obesity, resulting in an impaired uroguanylin-GUCY2C endocrine axis in the obese state." (PMID 37274331, 2023). "The present studies examine a novel pathophysiological mechanism contributing to obesity in which calorie-induced suppression of intestinal uroguanylin silences hypothalamic GUCY2C regulating satiety." (PMID 27214655, 2016). "Given the role of uroguanylin in opposing DIO,6, 7, 8 and the potential role of hypothalamic GUCY2C in mediating these responses, the present study suggests a novel pathophysiological paradigm contributing to calorie-induced obesity and its comorbidities." (PMID 27214655, 2016). "Clinical trials of linaclotide have shown it to be exceedingly well tolerated, lowering the regulatory burden for investigating the role of GUCY2C signaling in treating obesity." (PMID 26237477, 2014). "However, preservation of hypothalamic GUCY2C in DIO suggests the feasibility of a therapeutic paradigm involving cognate ligand replacement to manage obesity and its comorbidities." (PMID 27214655, 2016). "A decrease in GUCA2A mRNA and protein expression (both P<0.05) was found in the pancreas of rats with diet-induced obesity, whereas GUCA2B and GUCY2C gene and protein differences fell out of statistical significance." (PMID 37274331, 2023). "Guanylyl cyclase C (GUCY2C) is a membrane-bound receptor that, upon activation by the hormone ligands guanylin or uroguanylin, produces the second messenger, cGMP, controlling intestinal homeostasis, cancer, and obesity." (PMID 38243252, 2024). "Expression of uroguanylin and guanylin, but not GUCY2C, is reduced in small and large intestine, respectively, by diet-induced obesity in mice and humans." (PMID 29035170, 2017). "Colon cancer-related genes such as Nek11, Gucy2c, Srp9, Tle6, and Pdgfrl were also overrepresented in the time-course clusters identified by the MNI analysis in the epididymal and subcutaneous fat tissues and gastrocnemius muscle of mice with diet-induced obesity." (PMID 23555558, 2013). "An upregulation of GUCA2A and GUCY2C, but not GUCA2B, was observed in pancreata from rats with diet-induced obesity one month after sleeve gastrectomy." (PMID 37274331, 2023).
inflammatory bowel disease (14 papers, 2012 to 2024). A spectrum of small and large bowel inflammatory diseases of unknown etiology. "Similarly, inflammatory bowel disease (IBD) is associated with a loss of components of the GUCY2C signaling axis." (PMID 29262534, 2017). "Particularly, GUCY2C has been found to play a regulatory role in intestinal inflammation and inflammatory bowel disease pathology." (PMID 37927469, 2023). "Further, in murine models of tumorigenesis or inflammatory bowel disease, in which injury and recovery characteristically involve ISCs, silencing GUCY2C amplifies pathophysiology, tissue damage, and mortality." (PMID 29262534, 2017). "Recently, we reported that GUCA2A, GUCA2B and GUCY2C, plus several steps of the GC-C signaling pathway, are down-regulated in inflammatory bowel disease (IBD)." (PMID 27044258, 2016). "Moreover, it is tempting to speculate that loss of paracrine hormone expression and silencing of GUCY2C in inflammatory bowel disease produces systemic genotoxicity which contributes to the pattern of extra-intestinal cancer in these patients specifically in lymph nodes, liver, and lung." (PMID 22384056, 2012). "GUCA2A, GUCA2B, and GUCY2C are downregulated in inflammatory bowel disease, which may have implications in inflammatory bowel disease pathogenesis." (PMID 31467713, 2019). "On the one hand, if cGMP signaling exacerbates barrier disruption resulting in inflammation, then GUCY2C antagonists could be therapeutic in inflammatory bowel disease." (PMID 22384056, 2012). "Conversely, if cGMP signaling defends the barrier and prevents ensuing inflammation, then GUCY2C agonists could be a significant addition to the therapeutic armamentarium against inflammatory bowel disease." (PMID 22384056, 2012).
colitis (11 papers, 2012 to 2025). Inflammation of the colon. "Taken together, our results show that S839I mice harboring an activating mutation in Gucy2c reveal roles of cGMP in regulating gut function and enhanced colonic susceptibility to damage in a colitis model." (PMID 34546338, 2021). "DSS induced colitis with a 3-fold greater severity, quantified by maximum weight loss, in Gucy2c−/−, compared to Gucy2c+/+, mice." (PMID 22384056, 2012). "Also, DSS colitis was associated with >80% mortality in Gucy2c−/− mice, compared to Gucy2c+/+ mice which exhibited 100% survival." (PMID 22384056, 2012). "In an apparent contradiction to experiments with Gucy2c−/− mice, Gucy2cS839I/S839I mice, with higher GC-C activity, also showed increased susceptibility towards DSS-induced colitis and possessed a basal pro-inflammatory signature in their gut." (PMID 40801095, 2025). "GUCY2C is involved in the relief of intestinal inflammation and visceral pain during colitis and diarrhea, which are symptomatic in the acute and lethal phases of CSF." (PMID 40006915, 2025). "Conversely, enhancing GUCY2C signaling defends the integrity of the intestinal epithelial barrier from disruption by DSS, preventing the associated colitis." (PMID 22384056, 2012). "Further, silencing GUCY2C exacerbated, while activation reduced, chemical barrier disruption and colitis." (PMID 22384056, 2012). "The pathophysiological significance of this role in intestinal barrier protection is underscored by the impact of GUCY2C signaling on colitis and systemic genotoxicity and tumorigenesis." (PMID 22384056, 2012). "Here, the contribution of GUCY2C to barrier integrity opposing colitis and systemic tumorigenesis is defined." (PMID 22384056, 2012). "Beyond the inconsistencies in these observations from the same group, they stand in striking contrast to the results presented herein, demonstrating that GUCY2C signaling defends mucosal integrity against barrier disruption and colitis produced by DSS." (PMID 22384056, 2012). "Importantly, the interplay between the Gucy1A and Gucy2C transmembrane proteins emerges as a promising avenue for future therapeutic intervention in colitis." (PMID 39308187, 2024). "Abundant evidence supports the notion that the Gucy2C‐cGMP signaling axis counteracts intestinal epithelial damage and tumorigenesis underscoring the potential of targeting endogenous Gucy2C and Gucy1A transmembrane proteins in the later stages of colitis therapy." (PMID 39308187, 2024). "Thus, GUCY2C defends the intestinal barrier, opposing colitis and systemic genotoxicity and tumorigenesis." (PMID 22384056, 2012). "Following the induction of colitis by DSS, transcript levels of Gucy2c and Guca2a were reduced in both wild type and S839I mice." (PMID 34546338, 2021).
colorectal tumors (8 papers, 2010 to 2025). "GUCY2C protein (> 200 specimens) and/or mRNA (> 900 specimens) is present in nearly all primary and metastatic human colorectal tumors, regardless of anatomical location or grade, and is over-expressed by > 80% of colorectal tumors." (PMID 31010434, 2019). "Moreover, GUCY2C is over-expressed in colorectal tumors, with the apical restriction observed in epithelial cells being lost in malignant cells." (PMID 28914772, 2017). "Importantly, GUCY2C is expressed in greater than 80% of colorectal tumors, with both protein and mRNA expression identified in the majority of primary and metastatic lesions regardless of disease stage or tumor grade." (PMID 28914772, 2017).
metastatic colorectal cancer (6 papers, 2016 to 2025). "Guanylyl cyclase C (GUCY2C) is a membrane-bound protein found on the apical surfaces of intestinal epithelial cells, but is also a cancer mucosa antigen that is overexpressed in both primary and metastatic colorectal cancers as well as esophageal and gastric cancers." (PMID 30031396, 2018).
metastatic tumor (5 papers, 2010 to 2023). "While anatomic compartmentalization coupled with general association with metastatic disease suggest unique utility as a therapeutic target, the cellular dynamics of GUCY2C, beyond its expression at the cell surface, has remained incompletely defined." (PMID 25294806, 2014).
diarrheal disease (4 papers, 2010 to 2021). The condition of having at least three loose or liquid bowel movements each day. "The lack of models for diarrheal disease mediated by hyperactive GC-C to investigate the link between GC-C, cGMP, and gut inflammation prompted us to develop a mutant mouse harboring a mutation in Gucy2c, equivalent to the S840I mutation found in the Norwegian family." (PMID 34546338, 2021).
ulcerative colitis (4 papers, 2016 to 2025). An inflammatory bowel disease involving the mucosal surface of the large intestine and rectum. "Activating mutations in GC-C in cases of familial GUCY2C diarrhea syndrome (FGDS) as well as decreased expression of GC-C in ulcerative colitis (UC) suggests that precise GC-C signaling is important to maintain intestinal health and homeostasis." (PMID 33431701, 2021).